MANF (mesencephalic astrocyte derived neurotrophic factor)
Diseases named in the same sentence as MANF in open-access papers (continued):
Sharing a sentence is not in itself a finding about the gene and the disease.
type 2 diabetes (11 papers, 2016 to 2024). "MANF mutations have been reported in a patient with type 2 diabetes." (PMID 32366942, 2020). "Thus, it is of interest to study the association of MANF with insulin resistance and type 2 diabetes, as well." (PMID 27356471, 2016). "Moreover, it has been reported that the level of circulating MANF in the blood is elevated in patients with both T1D and type 2 diabetes (T2D)." (PMID 39666939, 2024). "Nevertheless, our study paves the way to develop MANF-based therapies for human disorders, including β cell death in type 1 and type 2 diabetes, neurodegenerative diseases, and Wolfram syndrome characterized by juvenile onset-diabetes, optic nerve atrophy, and neurodegeneration." (PMID 33299977, 2020). "Furthermore, increased circulating MANF levels have been detected in the sera of patients with type 1 and type 2 diabetes." (PMID 33299977, 2020).
depression (8 papers, 2019 to 2024). "In contrast, decreased levels of MANF in the serum have been reported in adult patients with growth hormone deficiency, major depressive disorder, nonalcoholic steatohepatitis, and polycystic ovary syndrome." (PMID 37555005, 2023). "There hasn’t been enough investigation into how MANF affects depression, but its association with depression could be predicted from these study findings." (PMID 38216957, 2024). "As it has already been proven that stress can act as a potential risk factor for depression and induce inflammation, by negatively inducing inflammation, MANF may reduce depression risk." (PMID 38216957, 2024). "So, there might be an association between high serum MANF level and the progression of depression." (PMID 38216957, 2024). "We recommend more investigation, including a significant population, to determine the precise function of IL-33 and MANF in depression." (PMID 38216957, 2024). "The current study proposes that lower IL-33 and higher MANF serum levels are associated with MDD progression and depression severity." (PMID 38216957, 2024). "In major depressive disorder, the MANF/EWSR1/ANXA6 pathway has been suggested as a potential link between hypolipidemia and major depression." (PMID 39722850, 2024). "For example, it has been reported that MANF levels in serum are higher in PD patients classified as depressed based on Beck Depression Inventory scoring." (PMID 36478320, 2023). "Moreover, the severity of depression would be measured by the altered IL-33 and MANF levels, if any." (PMID 38216957, 2024). "Furthermore, circulating MANF levels correlated positively with the depression rating of PD patients." (PMID 37555005, 2023). "Further investigations of MANF in MDD can help us better understand the role of lipids in the onset and development of depression, as the results may provide a valuable network among serum lipids, MANF and MDD." (PMID 36585419, 2022). "Therefore, the present study was conducted to assess the changes of serum lipid levels in MDD patients and investigate the potential role of lipid metabolism regulator MANF in depression." (PMID 36585419, 2022). "It is unclear whether the observed increase in MANF is directly related to depression, or whether it reflects PD pathophysiology leading to depression." (PMID 31555085, 2019). "The results showed that compared to HCs, MDD patients had a significantly lower level of MANF and higher levels of ANXA6 and EWSR1, and these molecules were significantly correlated with both TC level and Hamilton Depression Rating Scales (HDRS) score." (PMID 36585419, 2022). "Here, we found that the serum MANF level was significantly decreased in MDD patients, and significantly correlated to depression severity (negatively) and TC level (positively)." (PMID 36585419, 2022). "Third, we only detected MANF/EWSR1/ANXA6 pathway in serum, future studies should directly detect the levels of these molecules in the central nervous system, such as cerebrospinal fluid, to further pinpoint the role of this pathway in depression." (PMID 36585419, 2022). "Meanwhile, MANF, EWSR1, and ANXA6 were significantly correlated to TC concentrations and depression severity, and they could be potential biomarkers for diagnosing MDD." (PMID 36585419, 2022). "Besides, MANF, EWSR1, and ANXA6 were found to be significantly altered in the serum of MDD patients and correlated with serum lipid and the severity of depression symptoms." (PMID 36585419, 2022). "Circulating MANF concentrations were significantly higher in PD patients compared to controls (P < 0.001) and were positively correlated with Beck Depression Inventory (BDI) depression rating." (PMID 31555085, 2019). "Moreover, based on the IPA database analysis, we hypothesized that MANF/EWSR1/ANXA6 pathway might act as a bridge between low serum lipids and depression." (PMID 36585419, 2022).
depression (continued). "Circulating concentrations of CDNF were not altered in PD patients while MANF concentrations were significantly increased and positively correlated with the Beck Depression Inventory scoring, which is used to measure the severity of depression." (PMID 34907395, 2022).
hepatocellular carcinoma (8 papers, 2020 to 2025). A malignant tumor that arises from hepatocytes. "Still, the recent study on MANF associating ER stress and inflammation in hepatocellular carcinoma brings the attention back to cancer again." (PMID 36185184, 2022). "Meanwhile, MANF is overexpressed in hepatocellular carcinoma and can be used as a potential diagnostic and prognostic indicator for hepatocellular carcinoma." (PMID 36291587, 2022). "The latest study linked MANF to hepatocellular carcinoma via ER stress and inflammation." (PMID 36185184, 2022). "To assess the effect of MANF on β-catenin stability, we performed a CHX chase assay on hepatoma cells overexpressing MANF." (PMID 39289348, 2024). "Here we found that IFN-γ induced MANF secretion from diverse tumor cell-lines—melanoma cells, colon carcinoma cells and hepatoma cells." (PMID 33891607, 2021). "It’s more interesting that we found MANF was downregulated in hepatocellular carcinoma (HCC) and inhibited HCC progression, while it was upregulated in ICC, another primary liver cancer." (PMID 39972058, 2025). "The authors suggested that MANF could suppress hepatocyte inflammation by inhibiting the NF-κB/Snail signaling pathway and reduce the invasive and migratory capacity of hepatocellular carcinoma cells by interfering with the hepatocyte epithelial-mesenchymal transition." (PMID 38164189, 2024). "CALR as a Ca2+-binding chaperone located in ER lumen is responsible for modulating proper folding of neo-synthesized glycoproteins and for calcium retention; however, MANF as a negative regulator of unfolded protein response could alleviate hepatocellular carcinoma by suppressing EMT." (PMID 36639674, 2023). "However, this study shows that MANF was highly expressed in ICC tissues, while there was no significant change in MANF level in extrahepatic cholangiocarcinoma, although they are primary carcinoma of the liver." (PMID 39972058, 2025).
Hepatic steatosis (6 papers, 2020 to 2025). Steatosis is a term used to denote lipid accumulation within hepatocytes. "Liver-specific MANF knockout mice develop hepatic steatosis, whereas MANF overexpression reduces hepatic lipid accumulation." (PMID 40243151, 2025). "A recent study revealed that hepatocyte-derived MANF prevents hepatic steatosis, while immune cell-derived MANF protects against liver inflammation and fibrosis." (PMID 36635421, 2023). "Hepatic MANF overexpression improved adipose inflammation, insulin sensitivity and hepatic steatosis in HFD-fed mice." (PMID 37928262, 2023). "In summation, S100a16 ablation augmented MANF expression, thereby curtailing ER stress, which in turn mitigates the progression of alcoholic fatty liver development." (PMID 37928262, 2023). "Overexpression of MANF in the liver resulted in suppression of adipose inflammation, improved insulin sensitivity, and hepatic steatosis." (PMID 35012677, 2022). "In contrast, liver-specific MANF depletion exacerbated obesity, insulin resistance, and hepatic steatosis." (PMID 35012677, 2022). "MANFΔHep mice displayed signs of hepatic steatosis and more severe liver injury with increased ALT and AST levels than WT mice after alcohol feeding, suggesting that hepatocyte MANF-deficient mice are more susceptible to ALI." (PMID 32724497, 2020).
Insulin resistance (6 papers, 2016 to 2024). Increased resistance towards insulin, that is, diminished effectiveness of insulin in reducing blood glucose levels. "MANF, an endoplasmic reticulum stress-secreting protein, is strongly associated with insulin resistance and abnormal lipid metabolism under AGHD conditions." (PMID 34220710, 2021). "In the present study, lower tertile MANF concentrations had the highest odds ratio for disease, whereas in the AGHD population, higher MANF was positively associated with insulin resistance and lipid deposition." (PMID 34220710, 2021). "In animal models, MANF-/- mice show abnormal pituitary hormone secretion accompanied by a state of insulin resistance and growth hormone deficiency, while the mice exhibit severe growth retardation and endocrine gland atrophy." (PMID 34220710, 2021). "Next we aimed to study the mechanisms underlying MANF-mediated insulin resistance by exploring its interacting partners via affinity-purification mass spectrometry." (PMID 28924165, 2017). "If the enhanced ER localization and activity of PIP4k2b underlies MANF-mediated insulin resistance, reducing PIP4k2b should alleviate the impaired insulin response." (PMID 28924165, 2017). "Evidence suggests that AGHD patients with insulin resistance may have a higher risk of cardiovascular morbidity and that MANF may be a good predictor for cardiovascular risk assessment in AGHD patients." (PMID 34220710, 2021). "Our previous finding that AAV-mediated overexpression of MANF in the hypothalamus leads to insulin resistance and hyperphagia agrees with this conclusion." (PMID 39425207, 2024). "It has previously been shown that MANF triggers insulin resistance by enhancing the activity of phosphatidylinositol 5-phosphate 4-kinase type-2 beta (PIP4k2b, a kinase known to regulate insulin signaling) localized to the endoplasmic reticulum." (PMID 34220710, 2021). "Altogether, these results support that hypothalamic insulin resistance resulted from increased MANF levels is a major contributor of hyperphagia in MANF transgenic mice." (PMID 28924165, 2017). "MANF has a significant correlation with insulin resistance in the AGHD state." (PMID 34220710, 2021). "However, the background of this experiment is that MANF transgenic mice overexpress MANF factor in the hypothalamus and exhibit insulin resistance." (PMID 34220710, 2021). "The most significant positive correlation was between the level of MANF and insulin resistance." (PMID 34220710, 2021). "It has been shown that MANF interacts with PIP4k2b and triggers insulin resistance via an unknown pathway other than the inflammatory activation state." (PMID 34220710, 2021). "Similarly, serum MANF levels were increased in patients diagnosed with prediabetes and T2D, correlating with indexes of insulin resistance." (PMID 30386256, 2018). "It is noteworthy that insulin resistance was only found in tissues with increased MANF expression." (PMID 28924165, 2017). "These previous findings provided us a strong rational to investigate whether increased MANF augments PIP4k2b function to yield insulin resistance." (PMID 28924165, 2017). "Moreover, MANF triggers hypothalamic insulin resistance by enhancing the ER localization and activity of PIP4k2b, a kinase known to regulate insulin signaling." (PMID 28924165, 2017). "Thus, transgenic MANF triggers insulin resistance via certain mechanisms other than inflammation." (PMID 28924165, 2017). "To rule out the possibility that transgenic MANF causes insulin resistance via enhanced inflammation, we checked the phosphorylation levels of several inflammatory molecules: IκB kinase α/β (IKK α/β) and c-Jun N-terminal kinase (JNK) in the hypothalamus of 2-month old WT and MANF transgenic mice." (PMID 28924165, 2017).
steatosis (6 papers, 2019 to 2025). Increased lipid within the cytoplasm of cells. "Recent researches on MANF have concluded that liver-specific MANF ablation in mice caused progressive liver damage, fibrosis, and steatosis." (PMID 32724497, 2020). "Decreased MANF expression results in liver damage, steatosis, and fibrosis, while MANF supplementation improves diet-induced steatosis and age-related metabolic dysfunction." (PMID 40243151, 2025). "CD63, C-Type Lectin Domain Family 1 Member B (CLECB1), CD38, MANF, and Gamma-interferon-inducible lysosomal thiol reductase (IFI30) were all associated with steatosis grade in PWS." (PMID 39407757, 2024). "The causal role of MANF in hepatoprotection was confirmed by the findings that MANF heterozygous mice exhibit progressive liver damage, fibrosis, and steatosis and that overexpression of MANF confers protection against liver inflammation, fibrosis and hepatosteatosis." (PMID 40407975, 2025). "In addition, reduced MANF expression in tissues and sera of mice led to increased liver inflammation, fibrosis, and steatosis whereas MANF supplementation seemed to reverse age-dependent inflammatory and metabolic changes and induce rejuvenation in mice." (PMID 31781038, 2019).
autoimmune disease (5 papers, 2015 to 2024). A disorder resulting from loss of function or tissue destruction of an organ or multiple organs, arising from humoral or cellular immune responses of the individual to their own tissue constituents. "Here, we determined that ER stress inducible protein Mesencephalic Astrocyte-derived Neurotrophic Factor (MANF) was up-regulated in autoimmune diseases and inflammatory disease models." (PMID 25640174, 2015). "Of them 12 are associated with other autoimmune diseases than SLE, whereas three genes (ZNF804A, CDK1, and MANF) have not previously been associated with autoimmunity." (PMID 28740209, 2017).
Hepatic fibrosis (5 papers, 2022 to 2025). The presence of excessive fibrous connective tissue in the liver. "Recent data suggest that MANF deficiency in hepatocytes or hepatic monocyte/macrophages exacerbates hepatic fibrosis." (PMID 40243151, 2025). "Also, mono-macrophage-specific MANF deficiency significantly affects M1/M2 differentiation of splenic macrophages in the hepatic fibrosis process." (PMID 35911675, 2022). "Notably, systemic administration of recombinant human MANF markedly alleviates CCl4-induced hepatic fibrosis in both wild-type and hepatocyte-specific MANF knockout mice by targeting TLR4/NF-κB signaling." (PMID 40243151, 2025). "We have previously reported that recombinant human MANF (rhMANF) protein can relieve carbon tetrachloride (CCl4)‐induced hepatic fibrosis and lipopolysaccharide (LPS)‐triggered myocarditis, and rhMANF can be used in mice without any species difference or immune response." (PMID 40739335, 2025). "Previous studies showed that mice lacking MANF expression exhibit inflammatory phenotypes and aggravated tissue injury in various tissues, including progressive liver fibrosis and fatty degeneration." (PMID 40103332, 2025).
infarction (5 papers, 2015 to 2024). A localised pathological necrosis of tissue resulting from obstruction of the blood supply usually by a thrombus, an embolus, or vascular torsion. "In infarction and localized ischemic disease, MANF is secreted in large quantities after sarcoplasmic reticulum/endoplasmic reticulum calcium homeostasis is disrupted to prevent ischemic myocardial injury and has an antihypertrophic effect." (PMID 34220710, 2021). "MANF and TREM2 protein abundance is robustly increased after MCAo, and DHA treatment potentiated MANF abundance, decreased TREM2 expression, improved neurobehavioral recovery, reduced infarction, and provided enhanced neuroprotection." (PMID 32757264, 2020).
liver cancer (5 papers, 2021 to 2025). An epithelial or non-epithelial malignant neoplasm that arises from the liver. "We identified MANF as a biomarker for distinguishing the primary liver cancer and verified the oncogenic role of MANF in ICC using cell lines overexpressing/knocked down MANF and mice specifically knocked in/out MANF in hepatocytes." (PMID 39972058, 2025). "Sumoylation of mesencephalic astrocyte-derived neurotrophic factor inhibits the NF-κB/Snail signaling pathway and epithelial mesenchymal transition, thereby inhibiting the invasion and metastasis of liver cancer." (PMID 39742381, 2024). "At the same time, in vitro experiments show that MANF can also inhibit the metastasis and invasion of liver cancer cells." (PMID 34830854, 2021). "MANF is located in the nucleus and co-localises with liver cancer cells treated with p65 and tumour necrosis factor-α (TNF-α) in liver cancer tissues." (PMID 34830854, 2021). "In addition, the secreted protein mesencephalic astrocyte-derived neurotrophic factor (MANF) induced by ER stress inhibits epithelial-mesenchymal transition and NF-κB/Snail signaling pathway to relieve the invasion and migration of HCC, suggesting the conflict function of ER stress in liver cancer." (PMID 36388166, 2022).
microcephaly (5 papers, 2018 to 2022). A congenital or acquired developmental disorder in which the circumference of the head is smaller than normal for the person's age and sex. "Recently, recessive loss-of-function variants in MANF have been shown to cause childhood-onset diabetes, sensorineural hearing loss, microcephaly, and developmental delay." (PMID 34815294, 2022). "A homozygous MANF mutation was also associated with mild intellectual disability, microcephaly, and deafness, suggesting that MANF has a role in brain development and normal auditory function." (PMID 34907395, 2022). "Showing clinical relevance, the symptoms of a patient with type 2 diabetes mellitus, hypothyroidism, primary hypogonadism, short stature, mild intellectual disability, obesity, deafness, high myopia, microcephaly, and partial alopecia were likely caused by a mutation in MANF." (PMID 35783104, 2022).
neuroblastoma (5 papers, 2018 to 2025). Neuroblastoma (NB) is the most common solid, extracranial childhood tumor. "In an in vitro study, extracellular MANF was shown to protect human neuroblastoma SH-SY5Y cells from 6-hydroxydopamine (6-OHDA) induced cell death via the activation of PI3K/Akt/mTOR pathway." (PMID 33071755, 2020). "However, other studies have demonstrated that the KDEL‐R plays a crucial role in retaining MANF at the plasma membrane of neuroblastoma cells and rat cortical neurons following ER calcium depletion." (PMID 40827505, 2025). "Also, in vitro, recombinant MANF protects the SH-SY5Y neuroblastoma cell line from 6-OHDA-induced apoptosis." (PMID 35783104, 2022). "On the other hand, we first identified CRELD2 as a novel ER stress-inducible gene using microarray analysis of Tg-treated mouse neuroblastoma cell-line, Neuro2a3, and have been employing this Neuro2a cells to elucidate several ER stress gene expression (e.g., MANF, Chac1 and GADD153) in detail." (PMID 30111858, 2018). "Surprisingly, dantrolene did not attenuate extracellular MANF levels despite previously reported attenuation in SH-SY5Y neuroblastoma cell line, suggesting varying cell-specific responses." (PMID 35698232, 2022).
retinal degeneration (5 papers, 2018 to 2025). Degeneration of the retina. "This current study extended previous studies and provide further and necessary evidence for MANF's potential as therapeutic intervention of retina degeneration using two additional/different retinal degeneration models." (PMID 29687079, 2018).